APOB (apolipoprotein B)
Diseases named in the same sentence as APOB in open-access papers (continued):
Sharing a sentence is not in itself a finding about the gene and the disease.
type 2 diabetes (continued). "Parents of individuals with genetically elevated apoB had a lower risk of type 2 diabetes (fathers: OR 0·88, 95% CI 0·84–0·91, FDR-adjusted p=2·3 × 10–8; mothers: 0·92, 0·88–0·97, FDR-adjusted p=0·0042), whereas the decrease in risk was weaker in siblings (0·95, 0·90–0·998, FDR-adjusted p=0·082)." (PMID 34729547, 2021). "However, the protective effect of LDL cholesterol against type 2 diabetes became more pronounced (0·34 per 1 SD higher LDL cholesterol, 0·21–0·54) and a strong positive association between apoB and type 2 diabetes risk emerged (2·32 per 1 SD higher apoB, 1·49–3·61)." (PMID 34729547, 2021). "Also, increased OxLDL/apoB ratio was associated with peripheral neuropathy in type 2 diabetes." (PMID 27592002, 2017). "Recent studies have suggested that, beyond traditional lipid parameters, apolipoprotein A1 (ApoA1), apolipoprotein B (ApoB), and lipid ratios are particularly relevant in patients with type 2 diabetes." (PMID 41322311, 2025). "Several studies have reported that plasma apoB can predict type 2 diabetes, and plasma apoB has been reported to correlate with total insulin and C‐peptide in obese healthy individuals with a BMI > 27 kg/m2." (PMID 40129271, 2025). "From gene-level testing, the risk genes APOB and MYCBP2 were positively associated with serum liver enzymes, LiverRisk score, cirrhosis, and type 2 diabetes." (PMID 40065360, 2025). "The aim of this study was to evaluate the sex distribution of LDL/ApoB ratio among patients with type 2 diabetes (DM) and to assess, in both sexes, the correlations between key lipid parameters and LDL/ApoB < 1.2." (PMID 39420941, 2024). "However, the association of apoB with type 2 diabetes risk remains unclear." (PMID 36624450, 2023). "ApoA1, ApoB, and the ApoB/A1 ratio have been suggested as early indicators for predicting type II diabetes." (PMID 36329547, 2022). "A randomized, double‐blind clinical trial study showed that ginger extracts significantly improved the serum levels of fasting blood sugar, hemoglobin A1c, apolipoprotein B, apolipoprotein B/apolipoprotein A‐I, and malondialdehyde in type 2 diabetic patients." (PMID 35035916, 2022). "ε2ε2 carriers differed from ε3ε3 in having nominally lower pulse pressure and lower plasma apoB but otherwise had similar risk of IHD, similar SBP and DBP, and similar risk of type 2 diabetes and similar HbA1c." (PMID 33927215, 2021). "In MAFLD patients with type 2 diabetes, triglycerides had a dose–response relationship with moderate-to-severe steatosis in the multivariable-adjusted model (p for trend = 0.049), as did ApoB in the crude model (p for trend = 0.025)." (PMID 34899591, 2021). "With regard to cranberries, supplementation with cranberry juice was found to increase apolipoprotein A-I and decrease apolipoprotein B in patients with type 2 diabetes." (PMID 34444779, 2021). "ε3ε4 carriers differed from ε3ε3 carriers in having higher risk of IHD, pulse pressure and plasma apoB, but lower DBP, type 2 diabetes risk and HbA1c." (PMID 33927215, 2021). "In fact, epidemiological studies have shown that apoB predicts the development of type 2 diabetes as much as 3–10 years in advance of clinical onset." (PMID 34677405, 2021). "ε2ε4 carriers differed from ε3ε3 carriers in having lower SBP and plasma apoB, and nominally lower DBP, pulse pressure, but similar IHD and type 2 diabetes risk and HbA1c." (PMID 33927215, 2021). "In a previous study, we found elevation of lipids, lipoproteins, and the apoB/apoA-1 ratio to be present about 15 years before diagnosis of type 2 diabetes." (PMID 30138379, 2018). "In this study, we found that apolipoproteins and blood lipid levels, including serum TG, HDL, and ApoB levels, were highest in type 2 diabetic patients with early-stage DKD coupled with H. pylori infections." (PMID 29849820, 2018).
type 2 diabetes (continued). "This subgroup also had a greater prevalence of type 2 diabetes and multiple cardiovascular disease (CVD) risk factors, as well as increased levels of non–HDL-C and ApoB but lower HDL-C." (PMID 27240673, 2016). "It seems that oral administration of ginger powder supplement can improves fasting blood sugar, hemoglobin A1c, apolipoprotein B, apolipoprotein A-I, apolipoprotein B/apolipoprotein A-I and malondialdehyde in type 2 diabetic patients." (PMID 25561919, 2015). "The present study was conducted to investigate the effects of ginger on fasting blood sugar, Hemoglobin A1c, apolipoprotein B, apolipoprotein A-I, and malondialdehyde in type 2 diabetic patients." (PMID 25561919, 2015). "On the other hand, Framingham score increased with age, type 2 diabetes, and ApoB and it decreased with ApoA1, large HDL and Intermediate HDL." (PMID 25015177, 2014). "For both sexes, systolic and diastolic blood pressure, serum triglycerides, blood glucose, LDL-C and apoB, as well as the percentage of subjects with type 2 diabetes, showed a consistent increase with increasing BMI." (PMID 24228807, 2013). "The aim of this study was the effect of BVFE on serum lipoproteins, apoB, apoA-I, homocysteine, glycemic control and total antioxidant capacity in type 2 diabetic patients." (PMID 24250489, 2012). "Recent evidence suggests that apolipoprotein B (Apo-B) may be related to the onset of type 2 diabetes." (PMID 40642688, 2025). "High plasma levels of ApoB lead to white adipose tissue dysfunction and type 2 diabetes." (PMID 36788517, 2023). "Since ApoB is directly related to T2DM risk and R. ribes had ameliorative effects on both glycemic indices and apolipoproteins in the present study, it is likely to have a protective effect on type 2 diabetes." (PMID 36788517, 2023). "We sought to examine whether dietary intakes may affect the relationship between ApoB EcoRI and lipid profile, as well as serum inflammatory markers, in patients with type 2 diabetes (T2DM)." (PMID 35732646, 2022). "We decided to compare some inflammatory, and oxidative stress markers, as well as lipid profiles between the obese and non-obese patients with type 2 diabetes considering ApoB gene polymorphism." (PMID 35317787, 2022). "Moreover, three more variants were found in subject A, two VUS in the genes APOB and PKP2, and one likely pathogenic variant in the gene GCKR; this variant has been associated with a higher risk of type 2 diabetes." (PMID 36426223, 2022). "Inclusion of BMI in the multivariable mendelian randomisation for type 2 diabetes in DIAMANTE had no notable effect on the direct causal effects of apoB, LDL cholesterol, or triglycerides, which was also the case when accounting for WHRadjBMI." (PMID 34729547, 2021). "Similarly, reduced apoB48 (isoform of apoB) levels were observed after a fat-rich meal in patients with type 2 diabetes treated with 1.8 mg liraglutide." (PMID 31672146, 2019). "There are published reports that men with type 2 diabetes treated with simvastatin and bezafibrate had increased cholesterol efflux to apoB-depleted plasma and pitavastatin treatment has been reported to increase cholesterol efflux to total HDL in dyslipidemic subjects." (PMID 28207870, 2017). "Moreover, the APOA1/HDL cholesterol ratio was the strongest predictor of incident type 2 diabetes, and APOB level is significantly correlated with plasma insulin level in women." (PMID 28549478, 2017). "Emerging human studies have also shown associations of non-HDL cholesterol and ApoB with incident type 2 diabetes." (PMID 26859786, 2016). "Plasma apoB predicts the incidence of type 2 diabetes (T2D); however, the link between apoB-linpoproteins and risks for T2D remain unclear." (PMID 26417659, 2015). "Emerging human studies have also revealed associations of non-HDL cholesterol and ApoB with fasting glucose levels and incident type 2 diabetes." (PMID 26555648, 2015).
type 2 diabetes (continued). "The ratios of lipid and lipoprotein profiles, total cholesterol/HDL-C and ApoB/HDL-C, could be independently associated with later development of type 2 diabetes." (PMID 24093822, 2013). "When triacylglycerol is elevated, such as in people with type 2 diabetics, apoB (or non HDL cholesterol) is clearly superior but this may not be true in people with normal triacylglycerol levels." (PMID 16403234, 2006). "Furthermore, TRLs, ApoB and phenylalanine have been associated with CVD in people with CKD or type 2 diabetes, suggesting that the altered metabolome in DKD may partly explain the increased CVD risk." (PMID 38413437, 2024). "Findings in first-degree relatives were replicated in two-sample multivariable mendelian randomisation, which identified apoB to increase (OR 2·32 per 1 SD higher apoB, 95% CI 1·49–3·61) and LDL cholesterol to decrease (0·34 per 1 SD higher LDL cholesterol, 0·21–0·54) the risk of type 2 diabetes." (PMID 34729547, 2021). "ApoB increases in CKD patients are correlated with microalbuminuria and progression to overt nephropathy in type 2 diabetes, and renal deposition of ApoB accelerates the progression of glomerulosclerosis." (PMID 32242489, 2020). "The present study was conducted to investigate the effects of ginger on fasting blood sugar (FBS), Hemoglobin A1c (HbA1c), apolipoprotein B (Apo B), apolipoprotein A-I (Apo A-I), Apo B/Apo AI, and malondialdehyde (MDA) in type 2 diabetic patients." (PMID 25561919, 2015). "In this present study, we have investigated the effects of sumac (R.coriaria) on serum glycemic status, apoB, apoA-I and TAC in type 2 diabetic patients." (PMID 25587314, 2014). "In conclusion, these results showed the favorite effect of sumac consumption on serum glycemic status, apoB, apoA-I and TAC levels in in type 2 diabetic patients." (PMID 25587314, 2014). "The ratio of LDL-C/HDL-C, ApoB/ApoA1, ApoB/LDL-C and ApoA1/HDL-C and other variables were analyzed to determine their potential roles in type 2 diabetes in the Taiwanese population." (PMID 24093822, 2013). "Moreover, apoA-II (OR = 0.69, 95%CI: 0.54–0.88, p = 0.003) and apoB/non–HDL-C (OR = 0.75, 95%CI:0.60–0.94, p = 0.011) resulted as independent protective factors in the occurrence of type 2 diabetes, DR, and the severity of DR." (PMID 35937834, 2022). "In that study, chronic hyperglycaemia was significantly associated with elevated serum triglyceride and glycerol levels (consistent with findings in individuals with type 2 diabetes), yet not free fatty acids or apolipoprotein-B levels." (PMID 35406092, 2022). "Some studies have found that elevated dyslipidemia leads to lower bone turnover markers in patients with type 2 diabetes, but that there is a positive correlation between the LDL cholesterol/apolipoprotein B ratio and bone turnover markers in patients with type 2 diabetes." (PMID 36568987, 2022). "No clear effect of genetically predicted apoB on type 2 diabetes was identified in univariable mendelian randomisation." (PMID 34729547, 2021). "In patients with type 2 diabetes, we found generally a significant genotype effect; such that individuals with B1B1 genotype showed a significant decrease in apoB, apoB: apoA-1, insulin, and HOMA-IR and also an increase in QUICKI compared with B2B2 homozygotes." (PMID 33123324, 2020). "In patients with type 2 diabetes, B1B1 homozygotes compared with B2 carriers (B1B2 + B2B2) had a significant decrease in apoB levels (-19.05 ± 6.12 mg/dL) and apoB: apoA-1 ratio (-0.12 ± 0.04) and an increase in Lp(a) levels (6.37 ± 2.17 mg/dL) following the intake of sesame-canola oil." (PMID 33123324, 2020). "Yet, in a recent study performed in subjects with type-2 diabetes, apolipoprotein B and not LDL-cholesterol was able to predict subclinical carotid atherosclerosis." (PMID 24559258, 2014).
type 2 diabetes (continued). "In addition, TG-rich lipoproteins (after eating), remnant lipoproteins, apolipoprotein B 100 (ApoB), and small, dense HDL particles have also been shown to be increased in patients with type 2 diabetes." (PMID 21172030, 2010). "In well‐controlled type 2 diabetic patients, serum C‐peptide levels have earlier been reported to significantly correlate with BMI (r = 0.21), HDL‐c (r = −0.22), non‐HDL‐c (r = 0.23), triglycerides (r = 0.39), apoB (r = 0.29), and systolic and diastolic blood pressure." (PMID 40129271, 2025). "Carriers of the rs12740374 variant, which is associated with increased hepatic sortilin expression, have been consistently shown to have decreased LDL-C and apoB levels, but the relative decrease has not been compared in a metabolic stressed condition, such as the presence of type 2 diabetes." (PMID 35113816, 2022). "Moreover, L. usitatissimum seed powder (10 g/day for 1 month), containing not quantified ω-3 fatty acids and lignans, reduced fasting blood glucose, glycated hemoglobin, triglycerides, total and LDL cholesterol and apolipoprotein B, and increase HDL cholesterol levels in type 2 diabetes patients." (PMID 29300317, 2018). "Previously, oxLDL has been demonstrated to play a role in the development of DR since immunostaining of apolipoprotein B (apoB) oxLDL has been detected in the retinas of type 2 diabetic patients with or without DR and an increase in oxLDL levels reflects the severity of retinopathy." (PMID 28090539, 2016). "Therefore, the present study was planned to evaluate the effects of ginger powder supplementation on serum levels of fasting blood sugar (FBS), Hemoglobin A1c (HbA1c), apolipoprotein B (apo B), apolipoprotein A-I (apo A-I), Apo B/Apo A-I, and malondialdehyde (MDA) in type 2 diabetic patients." (PMID 25561919, 2015). "Therefore, in the present study, we performed a randomized, double-blind, placebo-controlled trial to evaluate the effects of Berberis vulgaris fruit extract on serum lipoproteins, apoB, apoA-I, homocysteine, and glycemic control and total antioxidant capacity (TAC) in type 2 diabetic patients." (PMID 24250489, 2012). "An analysis of patients enrolled in single-center, cross-sectional community-based studies at the University of Pennsylvania found that in Caucasians with type 2 diabetes, plasma apoB, but not LDL-C, may be an indicator of coronary artery calcification beyond traditional risk factors." (PMID 34677405, 2021). "In patients with type 2 diabetes and hypercholesterolemia or mixed dyslipidemia treated with statins, PCSK9 inhibitors significantly reduced LDL-C, non-HDL-C and apoB levels." (PMID 36936164, 2023). "The importance of changes in apolipoprotein B and non-HDL-cholesterol levels appears greater with fibrate therapy than with statin use, particularly in patients with type 2 diabetes." (PMID 15571637, 2004). "CYP8B1 mutation carriers showed decreased total cholesterol/HDL-C and APOB/APOA-I ratios, suggesting that CYP8B1 inhibition may reduce type 2 diabetes without proatherogenic lipid changes." (PMID 36107630, 2022).
hyperlipidemia (169 papers, 2005 to 2026). "Although CAIDE measures hyperlipidemia based on cholesterol levels, recent studies have highlighted the potential value of ApoB in more accurately assessing risk." (PMID 39863319, 2025). "Among these proteins, the association between APOB and hyperlipidemia was validated using external datasets, which made the results more reliable." (PMID 39474612, 2024). "Consistent with our findings, previous studies have shown that SNPs in APOB are associated with hyperlipidemia in Chinese and Finnish populations." (PMID 39474612, 2024). "Variants of APOB, which encodes the main lipoprotein in LDL-C, are associated with early onset AD, and overexpression of ApoB in mice results in hyperlipidemia, neurodegeneration, increased APP expression, and amyloid plaques." (PMID 39586400, 2024). "In contrast, 26.16% of the subjects had a risk GG or GA genotype of rs1042034 (APOB) for its correlation to hyperlipidemia and ischemic stroke." (PMID 36050800, 2022). "In the multivariate analyses in our study, the ApoB/ApoA1 ratio was a stronger risk predictor of IS than hyperlipidaemia, the WHR and HDL-C levels." (PMID 34082746, 2021). "The haplotypes of rs501120A-rs1746048T increased and rs501120G-rs1746048C decreased the risk of hyperlipidemia (P < 0.001 for each), showing consistent association with the levels of serum triglyceride, ApoA1 and ApoB." (PMID 31862910, 2019). "We investigated the influence of apolipoprotein B gene (APOB) variants on the risk of hyperlipidemia (HL) in 631 middle-aged and elderly members of the Chinese Yugur population (HL, n=336; normolipidemia, n=295)." (PMID 28902930, 2017). "Taken together, her ApoB and lipid levels were consistent with hyperlipidemia and her hemoglobin A1c was in the range diagnostic for type 2 diabetes." (PMID 24954083, 2014). "This technique should also be adaptable to study LDL obtained from families with other rare APOB variants, in order to establish the range of mutations in APOB which cause hyperlipidemia." (PMID 24498611, 2013). "Second, we showed that PCSK9-deficiency is associated with reduced postprandial hyperlipidaemia in mice challenged with an olive oil bolus, due to decreased apoB output and a modification of chylomicron size, number and catabolism." (PMID 23298392, 2013). "For example, using the SNPs reported in seven studies as genetic instrumental variables, the risk of hyperlipidemia was augmented by increased APOB (OR = 3.28; 95% CI, 1.78–6.04; P = 1.44e-04), NCAN (OR = 1.41; 95% CI, 1.16–1.71; P = 4.73e-04), and PCSK9 (OR = 1.39; 95% CI, 1.25–1.54; P = 1.00e-09)." (PMID 39474612, 2024). "Family members encode integral membrane proteins that mediate calcium-dependent cell-cell adhesion Variants of this gene have been associated with triglycerides, total cholesterol, and apolipoprotein B levels in families with hyperlipidemia, suggesting their association with lipid abnormalities." (PMID 31752434, 2019). "Indeed, a number of studies show that reductions in postprandial lipemia with n-3 fatty acids are associated with lower synthesis of apolipoprotein B-100." (PMID 25061524, 2014). "Collectively, the observed decreases in mRNA levels suggest that the improvements in hepatic lipid levels and associated hyperlipidemia found in the experimental group may be partially associated with decreased de novo cholesterol, lipid, and ApoB synthesis." (PMID 22027268, 2011). "Furthermore, studies in mice over-expressing ApoB suggest that hyperlipidemia predisposes mice to the formation of basal laminar deposits by altering hepatic and/or retinal pigment epithelium lipid metabolism." (PMID 17173705, 2006).